MET (MET proto-oncogene, receptor tyrosine kinase)
Diseases named in the same sentence as MET in open-access papers (continued):
Sharing a sentence is not in itself a finding about the gene and the disease.
hepatocellular carcinoma (continued). "On the other hand, the HGF/MET axis promotes the invasive growth of cancers; therefore, evaluation of HGF/MET targeted therapy is performed for hepatocellular carcinoma and cholangiocarcinoma (CCA)." (PMID 40076928, 2025). "Additionally, cabozantinib, targeting c-MET and the vascular endothelial growth factor receptor 2, is a second-line treatment for advanced hepatocellular carcinoma (HCC)." (PMID 39329778, 2024). "Tivantinib was developed as a MET inhibitor, received FDA orphan status, and underwent a phase III clinical trial for the treatment of hepatocellular carcinoma." (PMID 39470360, 2024). "Suppressing the downstream pathway of the HGF/MET axis, including phosphoinositide 3-kinase (PI3K)/AKT, RAS-RAF-MEK-ERK, and JAK/STAT, hinders the invasion and metastasis of hepatoma cells." (PMID 38881894, 2024). "Recently an elegant study was published, where RTK MET was described in a novel signaling pathway with FIS1/DRP1 that promotes mitochondrial fragmentation and metastasis in hepatocellular carcinoma cells." (PMID 35356277, 2022). "Cabozantinib is a tyrosine kinase inhibitor, known for inhibiting VEGFR, MET, and AXL, already in clinical use against multiple kinds of malignancies like hepatocellular carcinoma, sarcoma, and renal-cell carcinoma." (PMID 35719911, 2022). "The vast majority of the reported PTPN family members hold an inhibitory role in hepatocellular carcinoma (HCC), with the exception of PTPN11, which drives HCC progression by potentiating oncogenic proteins such as β-Catenin, PIK3CA and MET, and is associated with chemoresistance in HCC patients." (PMID 35957898, 2022). "Conversely, SOX2 overexpression decreased the level of MUC15 and increased the levels of c-MET, p-AKT in hepatoma spheroids, which further clarify that the MUC15/c-MET/PI3K/AKT/SOX2/miR-183-5p.1 regulatory circuit in liver T-ICs." (PMID 35236826, 2022). "Additionally, HCC patients with ETV1/PTK2 or ETV1/c-MET co-positive hepatocellular carcinoma in two different cohorts had a worse prognosis." (PMID 36407100, 2022). "One study found c-Met-directed CAR-NK-PBMC-derived (c-MET-directed CD8α.4-1BB.DAP12.CAR-NK-PBMC) cells to demonstrate high cytotoxicity against c-MET expressing HepG2 cells, a hepatocellular carcinoma cell line." (PMID 34072732, 2021). "Hepatocyte growth factor (HGF) and MET signaling supports cellular proliferation, promotes epithelial-mesenchymal transition (EMT) and causes invasion and metastasis during malignant transformation in hepatocellular carcinoma (HCC)." (PMID 32878084, 2020). "In contrast, the level of MET and EGFR were both decreased in TG hepatomas versus WT hepatomas, which was consistent with the findings in the liver regeneration model." (PMID 32489479, 2020). "Early stage human trials using T-cells modified to identify the c-MET and PD-L1 proteins (CAR T-Cells) for the treatment of primary hepatocellular carcinoma are planned." (PMID 32117721, 2020). "Up-regulation of C1GALT1 enhanced malignant phenotypes in colorectal cancer and hepatocellular carcinoma through FGFR2 and MET signaling pathways, respectively." (PMID 25762620, 2015). "In a phase 2 trial of tivantinib as a single agent for the treatment of hepatocellular carcinoma (HCC), significant improvement in OS (7.2 months vs. 3.8 months, HR = 0.38, p = 0.01) was observed in patients with high tumor MET expression." (PMID 28536405, 2015). "For example, tivantinib (also called ARQ197) and a dual inhibitor of c-MET/VEGFR2 (foretinib) were studied in phase I to II clinical trials in patients with papillary renal cell carcinoma and advanced hepatocellular carcinoma, respectively." (PMID 26225770, 2015).
hepatocellular carcinoma (continued). "In vivo studies in hepatocellular carcinoma has shown c-MET constitutive overexpression is required to drive these tumors, and inhibiting c-MET expression negatively affected the tumor." (PMID 24029073, 2013). "Research has shown that MET activates signalling pathways, such as the PI3K/AKT and RAS/MAPK pathways, promoting the proliferation, survival, and migration of hepatocellular carcinoma cells, as well as influencing vascular endothelial cells to promote neointimal formation." (PMID 39944086, 2025). "Besides, sustained activation of oncogene signaling such as RHO GTPase related signaling, HGF/c-MET signaling, PI3K/AKT signaling, NRAS/ERK signaling, is a key driver of hepatocellular carcinoma (HCC) progression." (PMID 38254216, 2024). "Likewise, c-MET has been shown to influence PD-L1 transcription via the MAPK/NF-κBp65 pathway, contributing to the progression of hepatocellular carcinoma." (PMID 39201787, 2024). "Moreover, overexpression of cellular MET (c-MET)/MET has been documented in diverse malignancies, including NSCLC, hepatocellular carcinoma, gastroesophageal cancer, and gliomas, further emphasizing their role in oncogenesis." (PMID 39668367, 2024). "Additionally, a computational model specific to hepatocellular carcinoma supports these findings, showing enhanced inhibition of phosphorylated AKT and ERK1/2 upon MET-α5β1 dissociation, highlighting the importance of MET-β1 co-trafficking." (PMID 39769452, 2024). "In that respect, Cabozantinib inhibits tyrosine kinases, including the VEGF receptors 1, 2, and 3, MET, and AXL, which are involved in the progression of hepatocellular carcinoma and the development of resistance to sorafenib, which is the conventional first-line treatment for advanced HCC." (PMID 38068521, 2023). "Thirdly, there is lack of persistent MET activation after sorafenib therapy in advanced hepatocellular carcinoma." (PMID 35711496, 2022). "In the hepatocellular carcinoma cell line Hepa 1–6, overexpression of JUN together with FOS could enhance the activity of MET, which also seems to be a downstream target of PA1." (PMID 35379345, 2022). "Furthermore, western blot analysis showed that MUC15 was downregulated and c-MET, p-AKT was upregulated in SOX2 knockdown hepatoma spheroids." (PMID 35236826, 2022). "Furthermore, miR-513c is markedly downregulated in hepatocellular carcinoma and glioblastoma (GBM) and overexpression of this miRNA prevented the proliferation of these cancer cells through targeting MET and Wnt/β-catenin signaling pathway, respectively." (PMID 34233668, 2021). "This impact of c‐MET on EMT has a drastic impact on cancer cell invasiveness and metastatic abilities, and is reflected in the upregulation of both c‐MET and HGF in circulating tumor cells (CTCs), as shown, for example, in hepatocellular carcinoma." (PMID 34542930, 2021). "In hepatocellular carcinoma, EGFR and c-MET cooperate to enhance resistance to PARP inhibitors." (PMID 32093123, 2020). "In hepatocellular carcinoma (HCC) invasive cell lines, in vitro and in vivo resistance to Sorafenib is caused by the distribution of hepatocyte growth factor (HGF), with the assistance of T-EVs and the subsequent activation of the HGF/c-MET/PI3K/AKT signalling pathway." (PMID 33081785, 2020). "In hepatocellular carcinoma (HCC) invasive cells lines, resistance to Sorafenib in vitro as well as in vivo was induced by delivery of hepatocyte growth factor (HGF) through EVs and subsequent activation of the HGF/c-MET/PI3K/AKT signaling pathway." (PMID 30925923, 2019). "Interestingly, others have found that hsa-miR-637 expression leads to downregulation of STAT3 activity in hepatocellular carcinoma cells and STAT3 is one of the downstream activated proteins of c-MET activity." (PMID 31063487, 2019). "In hepatocellular carcinoma, miR-198-5p has been shown to target the HGF/c-MET pathway." (PMID 29394946, 2018).
hepatocellular carcinoma (continued). "Considering EGFR and c-MET are preferentially overexpressed in hepatoma cells rather than hepatocytes, selectivity of ψ-Bufarenogin was thereby evaluated." (PMID 25890498, 2015). "MET overexpression, with or without gene amplification, has been reported in a variety of malignancies, including breast, colorectal, lung, gastric, and hepatocellular carcinoma." (PMID 26123926, 2015). "MET functions upstream of numerous signaling pathways promoting tumorigenesis including PI3K/AKT/mTOR, STAT, MEK/ERK, GRB2, GAB1 and RAC1 thus promoting cell survival, proliferation, angiogenesis and mobility and being similar to the tumorigenesis found in certain forms of hepatocellular carcinoma." (PMID 36421797, 2022). "Tivantinib has been described as a highly selective inhibitor of MET and is currently in a phase III clinical trial for the treatment of hepatocellular carcinoma (HCC)." (PMID 26458953, 2015). "Emerging evidence indicates that miR-198 is downregulated in hepatocellular carcinoma compared with in normal liver parenchyma, and forced expression of miR-198 inhibited HGF’s promotion of hepatocellular carcinoma cell migration and invasion in a c-MET-dependent manner." (PMID 24598126, 2014). "However, dysregulation of hepatocyte growth factor receptor (c-MET) significantly correlates with aggressive proliferation, invasive and pathological motility profiles in several malignancies, particularly NSCLC, gastrointestinal (GI) cancer and hepatocellular carcinoma (HCC)." (PMID 32545325, 2020). "Tivantinib, another TKI, is a non-ATP competitive c-MET inhibitor that is being investigated clinically as a highly selective MET inhibitor in NSCLC, hepatocellular carcinoma (HCC), and esophageal cancer." (PMID 35630066, 2022). "Indeed, HER2 blockade with afatinib, lapatinib, or trastuzumab did not demonstrate any antitumor efficacy in two METN375S-positive patient-derived xenografts (PDX) of hepatocellular carcinoma (HCC), in which phosphorylations of MET and HER2 were not prominent in the tumors." (PMID 32214092, 2020).
melanoma (276 papers, 1993 to 2026). A malignant, usually aggressive tumor composed of atypical, neoplastic melanocytes. "MYSM1 as a histone H2A deubiquitinase has been reported to activate the transcription of its downstream genes, including CDH1, c-MET, or genes encoding ribosomal proteins via histone H2A deubiquitination in colorectal cancer, melanoma, and B cell lymphoma." (PMID 38177530, 2024). "Among the differentially regulated miRNAs, miR-31 and miR-185 were known tumor suppressors in melanoma and hsa-miR-34b was shown to target the oncogene MET, which is associated with melanoma invasiveness." (PMID 35804857, 2022). "One of these mutational networks presented in melanoma was the one containing MET besides CARD11, CBLB, PPP6C and RAC1." (PMID 34885093, 2021). "The expression of MET (also known as hepatocyte growth factor receptors) associated with circulating EVs and phosphorylated MET (Tyr1349) was increased in patients with stage 3 and stage 4 melanoma compare to control." (PMID 34805181, 2021). "The specimen with most mutations harbored a gene alteration (T230M) in the SEMA domain of the MET gene, which mutated only in this melanoma." (PMID 32083130, 2020). "The obtained results validate the application of combination therapy directed against EGFR and MET in melanoma cells resistant to treatment with inhibitors of mutated BRAF." (PMID 31877948, 2019). "The synergistic effect of vemurafenib and tivantinib on cell viability was observed in c-MET-expressing melanoma cells that harbored a mutation leading to BRAFV600E." (PMID 30513872, 2018). "Next, we decided to investigate the effect of the tested inhibitors on the expression levels of selected proteins implicated in EGFR and MET signaling pathways in melanoma cell lines using Western blot analysis." (PMID 29719603, 2018). "MET pathway activation and dysregulation have been implicated in multiple cancers, including melanoma." (PMID 28103611, 2017). "MET fusion kinases occur in a mutually exclusive pattern with activating mutations of known melanoma oncogenes, and represent a potential therapeutic target in these patients." (PMID 29156643, 2017). "In a genomic survey, the gene encoding MET was amplified and overexpressed in metastatic melanomas compared with primary melanomas." (PMID 28103611, 2017). "Recent studies indicate the specific association of some proteins such as MET in the case of melanoma, and glypican-1 in the case of pancreatic cancer with exosomes, and their role in promoting the malignant transformation." (PMID 27086912, 2016). "Recently, in malignant melanoma a CDKN2A deficient mouse cell line demonstrated MET gene amplification." (PMID 25633809, 2015). "NRAS-mutated melanoma cell lines are sensitive to MET inhibition with regards to proliferation, migration and apoptosis." (PMID 25294187, 2015). "One case of melanoma (Lentigo Maligna type/stage IV disease) had 2 simultaneous c-MET mutations (N375S and T1010I)." (PMID 26097886, 2015). "Melanoma cells have been shown to release exosome-associated oncoprotein MET to educate bone marrow progenitor cells and promote metastases in vitro and in vivo, and elevated levels of MET and phospho-MET have been detected in melanoma patients." (PMID 25340037, 2014). "Thus, we investigated the expression of MET protein in canine melanoma and its association with histologic characteristics and clinical outcomes." (PMID 37104404, 2023). "In the present study, we further investigate their relationship by exploring the potential regulation of PD-L1 expression in melanoma by treatment with selective anti-MET tyrosine kinase inhibitors and the potential association between these two surface receptors." (PMID 37444518, 2023). "In addition, 10 out of the 19 patients have NRAS-mutated melanoma, a mutation that makes the tumor more pharmacologically susceptible to c-MET inhibition." (PMID 35954441, 2022). "Mutation of MET was considered to be a melanoma progression marker." (PMID 34885093, 2021).
melanoma (continued). "miR-34b, miR-34c, and miR-199a-3p are implicated in melanoma metastasis by targeting MET mRNA." (PMID 30866509, 2019). "In addition to the direct role of MET signalling in melanoma, HGF expression by stromal cells has been linked to innate resistance to RAF inhibitor treatment in melanoma patients." (PMID 28103611, 2017). "Moreover, amplification of the gene encoding MET has been implicated in acquired resistance to the BRAF inhibitor vemurafenib in cultured melanoma cells." (PMID 28103611, 2017). "It is plausible that in a tumor harboring concurrent c-MET aberrations, such as the one melanoma case in our review, the N375S mutation may hinder the efficacy of the c-MET directed treatment." (PMID 26097886, 2015). "Fedorenko and his colleague presented a preclinical study for NRAS‐mutant melanoma with amuvatinib, which is a multikinase inhibitor targeting mutant Kit, c‐MET, PDGFR‐α, and Rad51." (PMID 41492362, 2026). "Somatic mutations in SOX10 occur in early-stage melanoma, with SOX10 upregulating MITF, MET, and Nestin expression in melanoma and responding to Wnt signals." (PMID 41012776, 2025). "Wilms and team revealed that MYSM1 is involved in the regulation of survival‐ or proliferation‐relevant genes, like c‐MET, leading to the progression of malignant melanoma." (PMID 39212334, 2025). "In melanoma, several antigenic targets, including c-MET, CD70, VEGFR2, and GD2, have been investigated due to their roles in tumor growth, angiogenesis, and immune evasion." (PMID 40094890, 2025). "This study showed that exosomes promote angiogenesis and increase the permeability of pre-metastatic niches by activating receptor tyrosine kinase MET, thereby influencing the growth and metastasis of melanoma." (PMID 40666091, 2025). "Even though genetic changes in the MET gene are quite prevalent in certain types of tumors, particularly in melanoma and NSCLC, where more than 5% of patients have MET gene alterations, the incidence of MET fusions is still low in all cancer types." (PMID 38195556, 2024). "According to many reports indicating that drug resistance is often accompanied by overexpression of receptor tyrosine kinases (RTKs), the expression levels of EGFR, HER2, HER3, MET, and PDGFRβ receptors were verified in both resistant melanoma cell lines." (PMID 39175042, 2024). "Activation of the c-MET in brain-colonizing melanoma cells was found to promote tumor growth, potentially counteracting the effects of ICI therapy." (PMID 39582535, 2024). "The hepatocyte growth factor/MET pathway also plays a key role in melanoma development, progression, and therapeutic resistance." (PMID 39596009, 2024). "c-MET is highly expressed in various types of cancer including ovarian, breast, colon, and prostate cancers and melanomas." (PMID 38273381, 2024). "MET gene fusions also occur in melanomas, involving various N-terminal partners fused with the intracellular MET domain." (PMID 38675409, 2024). "In CD8+ T lymphocytes, c-MET expression enhances their cytolytic capacities ultimately providing greater efficacy in killing melanoma cells." (PMID 38909206, 2024). "Resistance-mediating processes include the phosphorylation of ribosomal protein S6 (pS6), which is downstream of MET and mTOR signaling and was observed in progressive BRAFi-resistant melanomas." (PMID 38386085, 2024). "Melanoma exosomes also stimulate vascular leakiness by reprogramming bone marrow progenitor cells via the receptor tyrosine kinase MET." (PMID 38353833, 2024). "Approximately 2% of glioblastomas and 12% of melanomas exhibited MET amplification according to whole-genome analysis." (PMID 38675409, 2024). "In conclusion, this is the first study to evaluate the level of MET expression with prognosis and survival in canine melanoma tissue samples." (PMID 37104404, 2023). "We also demonstrated the activation through phosphorylation of MET in key tyrosine kinase domains in canine melanoma cell lines through Western blots." (PMID 37104404, 2023).